UBE2SP1 (ubiquitin conjugating enzyme E2 S pseudogene 1)
Gene: Processed pseudogene on chromosome 17 (15,704,232 to 15,704,900, reverse strand). Ensembl gene ENSG00000233966.
Diseases named in the same sentence as UBE2SP1 in open-access papers:
UBE2SP1 is named in the same sentence as 1 disease in open-access papers, as found by Europe PMC text mining. Sharing a sentence is not in itself a finding about the gene and the disease.
UBE2SP1 shares sentences with these, for which no sentence is quoted: cancer (1 paper).